TLR7 (toll like receptor 7)
Diseases named in the same sentence as TLR7 in open-access papers (continued):
Sharing a sentence is not in itself a finding about the gene and the disease.
viral infection (continued). "The association of TLR7, TLR9, and Band 3 on the RBC surface during viral infection suggests a potential immune receptor complex on the RBC." (PMID 38982195, 2024). "TLR7 is mainly expressed by plasmacytoid dendritic cells (pDCs) which produce copious amounts of type I IFNs during viral infection." (PMID 39464882, 2024). "TLR7 recognizes pathogen-derived single-stranded RNA (ssRNA), a function integral to the innate immune response to viral infection." (PMID 38324161, 2024). "From a broad perspective, it would be interesting to further explore the role of c-Rel in other biologically relevant diseases involving TLR7, such as systemic lupus erythematosus and viral infections." (PMID 39586195, 2024). "Monocytes respond to viral infection or circulatory nucleic acids by means of TLR7/8, damage to endothelial cells using TLR7, and tumor metastasis control through CX3CR1." (PMID 37508391, 2023). "LILRA4 is a coreceptor that controls innate immune responses generated through FCER1G in viral infection and acts as a negative regulator of TLR7 and TLR9 signaling cascades." (PMID 37435086, 2023). "TLR7 has a potential protective role during the acute phases of viral infection by driving an early Th1 response in the lungs to evoke an antiviral response." (PMID 37795093, 2023). "Accumulation of LDs facilitates early innate response to viral infection through modulation of interferon signaling, in part via TLR7 and TLR9 pathways." (PMID 37298680, 2023). "Especially, the interferon signaling pathway was triggered a in TLR7-TRIF-IRF7-dependent manner upon virus infection in the oral yeast-immunized chickens." (PMID 37323887, 2023). "These molecules also act as TLR7 agonists to stimulate immune cells to produce interferons and interleukins to fight viral infections." (PMID 36188605, 2022). "TLR7 is mainly expressed by plasmacytoid dendritic cells and is crucial for host production of type I interferon during viral infection." (PMID 36317079, 2022). "Higher levels of TLR7 expression in females strengthens the immune response and likely provides an advantage in response to viral infections, including COVID-19." (PMID 35246245, 2022). "TLR7, an endosomal receptor expressed on dendritic and B cells, recognizes viral infections and triggers a type I interferon (IFN) response." (PMID 35246245, 2022). "Upon virus infection or agonist stimulation, TLR7 dimerizes in the endosome to initiate TLR7-mediated MyD88 signal transduction, resulting in the activation of mitogen-activated protein kinase cascades and NF-κB." (PMID 34952932, 2022). "For example, the use of an animal model elegantly demonstrates that TLR7-dependent type I interferon production by plasmacytoid dendritic cells (pDCs) confers protection against mouse hepatitis virus (MHV) viral infection." (PMID 35632741, 2022). "Isatoribine, 7-deazaguanosine, and loxoribine all are known Guanosine (G) analogs that can activate TLR7 and induce downstream immune responses to inhibit virus infection." (PMID 36188605, 2022). "Although unexpected, this is not a unique observation; a decrease in blood lymphocytes has been reported in patients and in animal models of acute viral infection, including after TLR7 stimulation." (PMID 34991643, 2022). "The expression levels of TLR7, Myd88, and NF-κB p65 mRNA were determined to study the effect of FTA on the TLR7 signaling pathway of viral infection." (PMID 35733131, 2022). "In vitro models suggest that β-estradiol can enhance the ability of plasma dendritic cells (pDCs) to respond to toll-like receptor 7 (TLR7) stimulation as a result of viral infection." (PMID 34878617, 2022). "Higher levels of TLR7, an endosomal receptor expressed on dendritic and B cells, which recognizes viral infections and triggers a type I interferon (IFN) response, have been found among women than men, and this provides an advantage in response to COVID-19." (PMID 35746709, 2022).
viral infection (continued). "Agonists to TLR7 are attractive therapeutic agents with the potential of activating innate and acquired immunity against viral infections, including HIV." (PMID 34356516, 2021). "IFNα/β production by pDCs is primarily mediated through the stimulation of TLR7 during viral infection, and is essential for the maturation of DCs to effective antigen‐presenting cells with increased ability to activate T cells." (PMID 33646622, 2021). "Upon viral infection, platelets are activated through TLR7 that change their phenotype and induce the formation of platelet-neutrophil aggregates." (PMID 34425822, 2021). "The transition from treating viral infections to malignant tumors using IMDs was bolstered by several mechanistic insights into the biology of these molecules as activators of TLR7/8." (PMID 34058283, 2021). "Taken together, our data suggest that both M-CSF and GM-CSF MФ are primed by virus infection to enhance TLR7-mediated cytokine induction." (PMID 33331816, 2021). "Upon recognition of viral infection, TLR7 triggers an antiviral type I interferon (IFN) response which serves to control viral replication and activate an adaptive immune response to clear the infection." (PMID 33646622, 2021). "Agonists to TLR7 are attractive therapeutic agents as they have the potential of activating both innate and acquired immunity against viral infections." (PMID 34356516, 2021). "Although we have focused here on viral infections, it is important to note the role that synthetic TLR7/8 agonists play as adjuvants in vaccines against bacterial infections." (PMID 34058283, 2021). "Our goal was to explore the difference between M-CSF- and GM-CSF-derived bone marrow MФ responsiveness to TLR7-mediated signalling pathways that influence cytokine production early after infection in a model of acute virus infection." (PMID 33331816, 2021). "Berberine also suppressed the viral infection-induced up-regulation of the TLR7 signaling pathway, such as TLR7, MyD88, and NF-κB." (PMID 34630083, 2021). "Family studies have allowed the identification of a polymorphism in the coding region of Toll-like receptor 7 (TLR7) gene determining a loss of function associated with a reduced IFN I and II response after viral infection." (PMID 33669011, 2021). "As key components of intercellular signal transmission and regulation, the expression of cytokines including inflammatory factors (IL-1β and IL-8) and toll-like receptors (TLR2, TLR3, and TLR7) increased significantly after viral infection." (PMID 33897703, 2021). "pDC are classified as the major type I IFN producing cells following viral infections by sensing viral RNAs via TLR7." (PMID 34473805, 2021). "The expression of both TLR3 and TLR7 was found to remain more of less stable at early time points following viral infection." (PMID 33799906, 2021). "To date, various small-molecule TLR7 agonists have been synthesized and many of them are under clinical trials for treating viral diseases such as hepatitis B and influenza and several types of cancer." (PMID 33060576, 2020). "An IFN response is also observed following viral infections in several fish species, and upregulation of both TLR7 and TLR8 transcripts was detected in infected Atlantic salmon." (PMID 32641385, 2020). "Viral infections or agonists of TLR7 or TLR9 can activate IRF5 in DCs in vitro in a MyD88-dependent manner." (PMID 31999809, 2020). "The signaling adaptor MyD88 has been demonstrated to activate IRF-7 for induction of type I IFN by pDCs in response to virus infection and TLR7/9 activation." (PMID 32373120, 2020). "Taken together, it is plausible that TLR7 plays a role in skewing B cells to generate IgG2a/c and IgG2b upon virus infection including EV71 infection." (PMID 33679702, 2020).
viral infection (continued). "This MyD88-IRF-7 pathway was found to operate mainly in pDCs, and is largely responsible for the rapid induction of high levels of type I IFN, following the activation of TLR7/8/9 by nucleic acids during viral infection." (PMID 32373120, 2020). "Yet, in the early acute phase, it appears to mimic more closely the physiological responses to viral infection, because of stimulation of the TLR-7 pathway." (PMID 31324689, 2019). "Finally, our identification of TLR7 as a host factor sustaining viral replication may serve as a potential target combined with IFN boosting adjuvants to prevent the establishment of early ssRNA pathogenic viral infections like rabies virus in humans." (PMID 30930901, 2019). "The crucial role of pDCs in antiviral responses involves sensing viral infection through TLR7 and TLR9, which results in the production of large amounts of IFN-I." (PMID 31093508, 2019). "It has been shown that TLR3 or TLR7 sense viral infection in the gut and trigger the production of IFN-β that dampens DSS-induced experimental colitis." (PMID 31130960, 2019). "Here we report that the CHIKV infection induces ROS- and TLR7-dependent NETosis, which in turn helps to control a viral infection and consequently protects the host." (PMID 32082301, 2019). "TLR7 recognizes single stranded RNA, and is thus of great importance in host defense against viral infection with HIV or Hepatitis C virus (HCV)." (PMID 31178872, 2019). "IFN-β, a type I interferon-stimulated by TLR7 in virus infection, was measured to monitor the effects of Ets2 in VSV treatment." (PMID 31785145, 2019). "pDCs are known for their ability to produce large amounts of type I interferon (IFN) in response to viral infection or stimulation by toll-like receptor-7 (TLR7) and TLR9-ligands." (PMID 31293597, 2019). "TLR-7 is a pattern recognition receptor involved in recognition of single-stranded RNA of viral origin and is thus crucial in host defense against viral infections." (PMID 31324689, 2019). "Here, we showed that Blimp-1 was induced in pDCs, the professional IFN-I producing cells that limit viral infection, after TLR7 and TLR9 stimulation." (PMID 30131810, 2018). "Together, these results indicate that virulent NDV blocks TLR7 expression but induces higher expression of type I IFNs in chicken macrophages at the late stage of viral infection." (PMID 29670609, 2018). "Inflammatory conditions such as viral infections associated with type I IFN production, increase TLR7 expression and can promote changes in protein glycosylation, and further affect CD22/TLR7 crosstalk." (PMID 30323814, 2018). "In both wild type and TLR7 KO mice, there was a significant difference in the lung index between the blank group and the virus control group (P < 0.01), indicating that the viral infection was successful." (PMID 30151032, 2018). "This specific role for TLR7 is remarkable in the light of the fact that viral infections trigger broader and more versatile immune responses compared to the treatment with immunostimulatory RNAs or even specific TLR ligands." (PMID 29497422, 2018). "We further demonstrated that virus infection increased protein expression levels of TLR7, MyD88, IRAK4 and NF-κB with western blotting, while Oseltamivir, Guizhi-and-Mahuang decoction, Yinqiao powder decreased their expression." (PMID 30151032, 2018). "EARs can also provide immune protection against virus infection in vivo in a mice model, where the eosinophil activation and virus clearance is mediated by a TLR7-signaling pathway." (PMID 29867984, 2018). "Upon viral infection, platelets are activated through TLR7, which induces a change in their phenotype, leading to the formation of platelet-neutrophil aggregates." (PMID 30258502, 2018). "When viral infections are detected by pDC via toll-like receptor 7 (TLR7) or TLR9, pDC produce interferon-α (IFN-α) and induce expression of antiviral factors for inhibition of viral replication and spread." (PMID 30071871, 2018).
viral infection (continued). "Virus infection induced significant increase in the mRNA levels of TLR7, MyD88, IRAK4 and NF-κB in wild type mice compared to blank control (P < 0.001)." (PMID 30151032, 2018). "The UNC93B1 H412R mutation, also called the 3D (or triple D) mutation, causes inefficient processing of TLR3, TLR7, and TLR9 and results in enhanced susceptibility to virus infection." (PMID 28928743, 2017). "Under these circumstances, it is likely that the cytokines induced by virus infection are responsible for triggering the induction of TLR7 expression." (PMID 28928743, 2017). "TLR7 can be triggered not only by ssRNA during viral infections, but also by immune modifiers that share a similar structure to nucleosides." (PMID 28620298, 2017). "Previously, TLR7 was considered to be an immediate and principal defense element against ssRNA viral infection prior to viral replication in the host after entry." (PMID 28265274, 2017). "We determined the genotype distribution of single-nucleotide polymorphisms (SNPs) within the TLR3 and TLR7 genes in children with HCMV infection and the relationship between TLR polymorphisms and viral infection." (PMID 28046022, 2017). "Agonists to TLR7 are attractive therapeutic agents with the potential of targeting innate and acquired immunity in fighting viral infections." (PMID 27799218, 2017). "Potentially this signifies Cys98 of TLR7 as a novel redox sensor that controls immune function during viral infections." (PMID 28701733, 2017). "pDCs represent by far the major type I IFN-producing cells in vivo in response to viral infections, during autoimmunity and even bacterial infection, through TLR7/ and TLR9/MyD88 sensing of nucleic acids." (PMID 27792766, 2016). "Plasmacytoid dendritic cells (pDCs) are known to produce a large amount of type I IFNs upon viral infection through the TLR7 and TLR9 system." (PMID 26384031, 2015). "TLR7 is thought to be exclusively expressed by plasmacytoid dendritic cells, which secrete type I interferons in response to viral infection." (PMID 26679344, 2015). "In conclusion, our study provides TRAM as a novel modulator of TLR7 mediated IRF3 activation serving as an additional element to tailor the host immune response to viral infection that mediates their effects through TLR7." (PMID 25211222, 2014). "pDCs typically respond to viral infection via endolysosome-localized TLR7- or TLR9 sensors that recognize RNA or DNA viral genomes, respectively." (PMID 25340500, 2014). "For example, it has been shown that viral infections can activate a broader set of intracellular innate immune receptors, such as TLR7 or TLR9." (PMID 24744264, 2014). "Single stranded viruses stimulate the production of IFN-α via different mechanisms i.e.; TLR7 recognizes viral RNA delivered to endosomal compartments in pDC and viral infection can elicit IFN-α responses via cytoplasmic sensors." (PMID 24303065, 2013). "PDCs are highly specialized immune cells that produce large amounts of type I IFNs in response to viral infection via, in part, TLR7 and TLR9." (PMID 24039973, 2013). "TLR7/8 agonists are primarily developed for treating viral diseases, but also as adjuvants for cancer and infectious disease vaccines." (PMID 24302927, 2013). "TLR3, TLR7 and TLR8 have been implicated in responses to virus infection in animal models, TLR3 through recognition of dsRNA and TLR7 and TLR8 through recognition of ssRNA and small nucleoside analogues." (PMID 23824215, 2013). "Viral infections are characteristically accompanied by type I interferon responses resulting from interaction of viral RNA with TLR7 and TLR3, for respectively single- stranded RNA or double-stranded RNA getting access to endosomal compartments." (PMID 24303065, 2013).
viral infection (continued). "Similarly, a recent report on HCV in vitro studies demonstrated that viral infection can specifically down regulate another receptor, TLR7 and envelope proteins have been directly linked to the blocking of the TRAIL pathway which could be mechanistically explained by the down regulation of RIG-I." (PMID 21695051, 2011). "Through the recognition of ssRNA derived from RNA viruses, TLR7 can also act as a danger receptor for viral infection." (PMID 22022401, 2011). "We found that TLR3 and TLR7 play an important role in controlling viral infection through the IFN production, while RIG-I play a role in IFN induction as well as in the induction of hepatocyte apoptosis." (PMID 21695051, 2011). "Toll-like receptors 7 and 8 (TLR7/8), which are activated by some viral infections, also mediate KSHV reactivation." (PMID 21625290, 2011). "Conversely, transfecting TLR3 or TLR7 into Huh7.5 cells, followed by viral infection, rendered the cells capable of IFN induction." (PMID 21695051, 2011). "Determining how TLR7 regulates the development of germinal center B cells during viral infection should be an area of further investigation." (PMID 21998589, 2011). "Production of high levels of IFN-I by pDCs in response to TLR7 or 9 ligation is entirely dependent on IRF7—this transcription factor is thus a “master regulator” of systemic production of IFN-I during virus infections." (PMID 21994626, 2010). "The induction of TLR3 (recognizing dsRNA) and TLR7 (recognizing ssRNA) suggests enhanced vigilance against viral infection activated by type I IFNs (MYD88 was also up-regulated)." (PMID 20339534, 2010). "pDCs play a vital role in the generation of innate and adaptive immunity following viral infection, primarily through the production of large quantities of IFNα in response to stimulus of TLR7 or TLR9 PRRs by ssRNA or DNA PAMPs, respectively." (PMID 20532161, 2010). "In response to systemic viral infection, pDCs produce type I IFNs by recognizing viral nucleic acids through TLR7 and TLR9, while production of type I IFNs in cDCs depends on RLH and cytosolic DNA sensors." (PMID 19479062, 2009). "A genetically determined lower capacity to produce ROS from the NOX2 complex could therefore be beneficial for the protection of virus infection, particularly ssRNA viruses, known to efficiently activate interferon signaling through TLR7 or STING." (PMID 39939342, 2025). "Although alternative PRRs, such as RIG-I and TLR7, might have an impact on viral infection in some circumstances, our data indicated that NLRP3 was the primary pathway mediated by macrophages in the recognition of IBV." (PMID 40906404, 2025). "Differential activation of these receptors—for example, TLR4 in sepsis or TLR7 in viral infections—may serve as a cellular signature of pathogen type." (PMID 40692784, 2025). "Additionally, TLR7 is involved in the occurrence and development of various other autoimmune diseases and immune-related conditions, such as rheumatoid arthritis and viral infections." (PMID 38429401, 2024). "Indeed, as shown in vitro, pDC IFN production during viral infections in vivo is driven by TLR7/9-dependent endosomal recognition of engulfed viral nucleic acids." (PMID 38777879, 2024). "We then examined whether HIV is sensed by TLR7 or TLR8 in the context of viral infection using an established model of cell-to-cell transmission." (PMID 37256770, 2023). "In theory, inhibition of the TLR7-mediated innate response to viral agents may be disadvantageous during the initial stages of viral infection." (PMID 36811819, 2023). "However, the mRNA and protein expression levels of MyD88 and NF-κB p65 in the lung tissues of TLR7-deficient mice infected with FM1 were similar between the forsythiaside A treatment group and the viral infection group." (PMID 37089926, 2023). "As TLR7 expression can be induced by interferon, we reasoned that gene expression in the black swan may only be detected in the presence of virus infection." (PMID 36683094, 2023).